CD4 (CD4 molecule)
Diseases named in the same sentence as CD4 in open-access papers (continued):
Sharing a sentence is not in itself a finding about the gene and the disease.
diabetes (continued). "AORs with 95% CIs from the final model, including age, employment status, family history of diabetes, CD4 count <200 cells/μL, and viral-load failure, are shown." (PMID 41399597, 2025). "In the univariate logistic regression, age, employment status, family history of diabetes, and CD4 count <200 cells/μL were significant predictors." (PMID 41399597, 2025). "The diabetes group that received vitamin D treatment had significantly reduced populations of CD4+ CD25+ and CD8+ CD25+ compared to the untreated diabetic group (p < 0.0001)." (PMID 39812046, 2025). "Subsequently, we considered age, sex, smoking status, diabetes, and hypertension as confounders and performed a multivariable analysis for the CD4+/CD8+ T cell ratio." (PMID 40165483, 2025). "On a non-obese diabetic background, mbd2 deficiency upregulates T helper cell 1 programs and exacerbates the development of autoimmune diabetes, and ectopic mbd2 expression in CD4+ T cells reduces the development of diabetes in an adoptive transfer model." (PMID 41198985, 2025). "Key measures included virologic outcomes (HIV-1 RNA < 50 or ≥ 50 copies/mL), CD4 T-cell changes, adherence, metabolic and renal parameters, treatment-emergent adverse events, and treatment-emergent diabetes and hypertension." (PMID 40846915, 2025). "Together, these events led to accelerated diabetes progression, suggesting that PD‐1 expression by CD4+ T cells promotes a tolerogenic microenvironment and restraining autoreactive CD8+ T cells." (PMID 40623940, 2025). "It has been demonstrated that IL32 is highly expressed by CD4+ T cells from people living with T1D, as assessed by single cell sequencing, in response to neo- and native epitopes of diabetes autoantigens." (PMID 40977709, 2025). "The other possible connection between OLP and diabetes is that the main metabolic route of these CD4+ and CD8 + lymphocytes is through glycolysis and the pentose phosphate pathways." (PMID 40429402, 2025). "PWH with high hsTnT were older, predominantly male, had lived with HIV for a longer duration, had higher prevalence of hypertension and diabetes and had a lower current CD4 count than PWH with low hsTnT." (PMID 40149937, 2025). "Forty-three of the included individuals had comorbidities (diabetes, hypertension, cardiovascular disease, or cancer), and the overall median CD4 cell count was 76 cells/μL." (PMID 40176257, 2025). "The mechanism shows that B cells from (Tlr7−/−) NOD mice suppress the CD4+ T-cell response to diabetes, protecting immunodeficient NOD mice from diabetes induced by diabetogenic T cells." (PMID 39776900, 2024). "Of note, the protection against diabetes seemed to level off around 50% with transfer of CD4+ and CD8+ T cells with reduced iPLA2β." (PMID 39359722, 2024). "After adjustment for age, sex, occupation, educational status, current CD4+ count (cells/mm3), history of previous hospitalization and diabetes status, history of catheterizations, and urgency of the urinary tract." (PMID 38820330, 2024). "We found that TLR5-deficient DCs are hyper cytokine secretors that can modulate antigen-specific CD4+ T cell proliferation, leading to increased diabetes development in older adult mice." (PMID 38482010, 2024). "Specifically, several reports show a significant link between diabetes and increased inflammatory CD4+ Th17 cell expression, and there have been a few studies showing that decreasing CD4+ Th17 cell expression in diabetes can lead to decreased pathogenicity." (PMID 38912581, 2024). "According to our flow cytometry results, the amount of CD3+ T cells and CD4+ T cells were the highest in the diabetes group." (PMID 39479688, 2024). "The logistic regression analysis was performed to find any association between CKD and diabetes, age, hypertension, BMI ≥ 25 kg/m2, alcohol use, and advanced HIV stage (CD4+ count <200)." (PMID 39056083, 2024).
diabetes (continued). "Patients who had low CD4 counts, previous hospitalization, diabetes status, and having history of catheterizations than their counterparts were more at risk of developing bacterial urinary tract infections." (PMID 38820330, 2024). "We found reduced severity of insulitis in the protected mice, with less infiltration of CD8+ T cells, CD4+ T cells as well as B cells compared with those that developed diabetes." (PMID 39351219, 2024). "Our patient suffered from HIV with a low level of CD4 T-lymphocytes (61 cells/μl), a history of diabetes and alcohol abuse, so he was prone to be infected by this bacterium." (PMID 38173032, 2024). "Cell counts of CD4+ T lymphocytes were evaluated between control, 2 mg/kg bW stevia, 25 mg/kg bW stevia, diabetes, diabetes +2 mg/kg bW Stevia, and diabetes +25 mg/kg bW stevia groups." (PMID 39479688, 2024). "Of the 1,392 assessable participants, 46% were female, the median age was 43, 14% were living with HIV (median CD4 count 378), and 14% were living with diabetes (median HbA1c 7.0)." (PMID 38947093, 2024). "The supplementation of soluble CD39 to pre-diabetic NOD mice reduces the extent of extracellular ATP, inhibits the multiplication of CD4+ T cells, and delays the further progression of diabetes." (PMID 38706698, 2024). "•The content of T-cells, testing NK cells, naive B-cells, and naive CD4 T-cells is relatively low in diabetes." (PMID 39096856, 2024). "The GAD65524-543 peptide in particular has been further implicated as a pathogenic epitope given that adoptive transfer of a TH1-like GAD65524-543-specific CD4+ T cell clone induces diabetes in NOD.scid mice." (PMID 39211046, 2024). "It is well established that CD4+CD25+ Tregs offer protection against diabetes in the NOD model, where they depend on IL-2 to exert their suppressive functions." (PMID 39704171, 2024). "Another report showed that IAg7/InsB:R3 reactive naive CD4+ T cells become effector T cells when mice age and develop diabetes." (PMID 37593744, 2023). "Another study reported that HDL‐C was inversely associated with CD4+ T subsets including interleukin (IL)‐8‐expressing CD4+ T cells and IL‐17‐expressing CD4+ T cells in diabetes mellitus patients with CAD." (PMID 36988256, 2023). "The delay in diabetes onset in the total splenocyte recipients was due to the presence of CD4+CD25+ regulatory T cells in the splenocyte population." (PMID 37600814, 2023). "To assess the prognostic potential of the %TSDR/CD4, we looked at clinical features developed during follow-up by patients who had initially presented with diabetes." (PMID 36600150, 2023). "CD4+ T cells play an important role in the pathogenesis of chronic systemic inflammatory autoimmune diseases such as multiple sclerosis, diabetes, and rheumatoid arthritis." (PMID 38032740, 2023). "They found that NOD-SCID mice receiving splenocytes from 6-week-old NOD mice developed diabetes 11 weeks after transfer, and those receiving diabetogenic CD4+CD25−CD62L− T cells from mice of the same age developed disease 5 weeks after transfer." (PMID 37600814, 2023). "We found that PWH with cardiometabolic diseases (non-alcoholic fatty liver disease, calcified coronary arteries, or diabetes) had higher circulating CGC+CD4+ T cells compared to metabolically healthy PWH." (PMID 36865544, 2023). "Together, this study suggests that among PWH, CGC+ CD4+ T cells are frequently CMV-specific and are associated with diabetes, coronary arterial calcium, and non-alcoholic fatty liver disease." (PMID 36865544, 2023). "This concept is further supported by epidemiologic analyses in PWH showing an association between a higher circulating CD4+ TEMRA cell frequency and the subsequent development of diabetes mellitus." (PMID 36865544, 2023). "Persons with diabetes had greater CD4 counts, earlier care, and greater virological suppression than persons without diabetes." (PMID 37442942, 2023).
diabetes (continued). "An imbalance of CD4+ T regulatory cells (Tregs) was also critical in the development of insulin resistance and diabetes." (PMID 36741233, 2023). "For example, T-helper type 17 (Th17) cells, an important pro-inflammatory CD4+ T-cell subset secreting interleukin 17 (IL-17), has been suggested to play an essential role in the development of diabetes mellitus." (PMID 37417730, 2023). "As FOXP3 + T cells can suppress many types of immune cells, such as CD4 + T cells and NK cells, they have the potential to suppress a wide spectrum of immunological diseases, such as diabetes." (PMID 37296126, 2023). "We show that circulating CGC+ CD4+ T cells and CGC+ CD8+ T cells in PWH are associated with prevalent cardiometabolic conditions (diabetes, subclinical atherosclerosis, and liver disease)." (PMID 36865544, 2023). "Diabetes in males (MD+ group) showed a reduced CD4 helper T cell population as compared to diabetic females (FD+ group)." (PMID 37881338, 2023). "Naidoo (2009) identified the herpes simplex virus, hepatitis, diabetes, lipodystrophy or a low CD4 count as contributory factors to difficulty swallowing pills and ultimately non-adherence." (PMID 37042519, 2023). "Our group has previously shown that CD4+ CD28- T cells are also increased prior to the development of incident diabetes in PWH." (PMID 36865544, 2023). "Cross‐sectional associations of higher CD28− and TEMRA CD4+ and CD8+ cells with prevalent diabetes have also been reported." (PMID 36333945, 2023). "His concomitant diseases were chronic hepatitis type B with liver cirrhosis, diabetes mellitus, osteoporosis, and hypertension, with a CD4 T-cell on vaccination—224 cells/μL." (PMID 37242997, 2023). "For instance, in obesity and type 2 diabetes, M2-like macrophages keep the adipocytes responding to insulin, and Th2 CD4 cells seem to protect from insulin resistance in obesity models, whereas Th1 CD4 cells drive diabetes." (PMID 35903540, 2022). "We investigated the effects of diabetes on the distribution of thymic T-lymphocytes in the three animal groups using anti-CD4." (PMID 35554836, 2022). "We observed that the main risk factors for a positive NI screening in HIV older adults were low education level, a nadir CD4+ T-cell count < 350 cells/mm3 and the presence of any comorbidity, highlighting diabetes among them." (PMID 35109939, 2022). "That is, PD-1 regulates islet responsive CD4+ T cells in a cellular manner by inhibiting proliferation, restraining pancreatic invasion and limiting diabetes mellitus." (PMID 36405706, 2022). "Based on this systematic review and Meta-analysis, UTI among people living with HIV in the Ethiopian context was done on sex, CD4 count, residence, history of catherization, and history of diabetes milletus." (PMID 35363782, 2022). "Immunocompromised patients also had significantly fewer CD3+CD4+ T-cells than diabetes mellitus patients and fewer CD3−, CD16/56+ natural killer (NK) cells compared to elderly patients." (PMID 35458476, 2022). "It has been reported that Mesenchymal stem cells have been shown to have an immunosuppressive effect by binding PD-L1 to PD-1 receptors on the surface of CD4+ T cells for the treatment of diabetes." (PMID 36056051, 2022). "It has been shown inter alia that patients with a higher frequency of CD4+CD25+CD127high lymphocytes at the onset of the diabetes, exhibited more extended period of remission during treatment." (PMID 36091019, 2022). "At × 400 magnification, we investigated the effect of diabetes on the distribution of T cells and B cells in the spleen using anti-CD4 and anti-CD19 antibodies." (PMID 35554836, 2022). "Therefore, with these data, we suggest that in T1D-associated alleles patients, the EBV infection of B cells may result in the presentation of viral determinants that act as peptide mimics to trigger the cross-reactivity of memory CD4 T cells with diabetes-associated antigens." (PMID 35894054, 2022).
diabetes (continued). "Another DEG identified in this study was CD4 enriched in the “breakdown of CD4+ T cell peripheral tolerance in type 1 diabetes mellitus” pathway in muscle, which was less expressed in the SOY1.5 group (log2-fold change −1.57)." (PMID 35804531, 2022). "Here, in wt NOD mice, we indeed found that an increase in the percentage of CD4+ Tregs in the pancreatic lymph nodes follows diabetes onset." (PMID 36291615, 2022). "There were significant differences in age, sex, diabetes, cerebrovascular disease, median haemoglobin level, and CD4+ T cell counts between the two groups." (PMID 35866793, 2022). "Subsequent studies with HPSE-1-deficient OT-II and OT-I T cells demonstrated, as expected, that antigen-activated CD4+ OT-II T cells are the dominant T cell population involved in diabetes induction." (PMID 35563015, 2022). "Currently, human patients with diabetes have shown consistent laboratory figures with low CD4+ and CD8+ T cell counts as well as elevated Th17 cells and other pro-inflammatory cytokines." (PMID 36051728, 2022). "It was shown that the disease was more severe and prolonged in the mice with diabetes, who also presented with abnormal CD4+ T cell counts as well as elevated IL17a." (PMID 36051728, 2022). "More importantly, compared with healthy WT mice, the pancreatic α4β7+CD8+ and α4β7+CD4+ T cells from diabetes-prone NOD mice showed an increased IFN-γ-secreting phenotype." (PMID 35547774, 2022). "Another similar study in diabetes, the sequence of TCRα and TCRβ showed limited overlap (<5%) between TCRs in a specific antigen reactive CD4+ T cells." (PMID 36233533, 2022). "Genes co-expressed with PTPN6 were correlated with “Immune response_T cell co-signaling receptors, schema”, “Breakdown of CD4+ T cell peripheral tolerance in type 1 diabetes mellitus”, and “Chemotaxis_SDF-1/CXCR4-induced chemotaxis of immune cells”." (PMID 36556168, 2022). "We found evidence that NOD Vγ4+ γδ T cells inhibit the development of diabetes, and that the process by which they do so involves IL-17 production and/or promotion of regulatory CD4+ αβ T cells (Tregs) in the pancreatic lymph nodes." (PMID 36291615, 2022). "After the adoptive transfer, diabetes was evident by 40 days in NOD.scid mice receiving Mbd2−/− CD4 T cells with all the mice developed hyperglycemia within 57 days, while a relative delay in terms of T1D development was observed in the control group." (PMID 34420035, 2022). "After adjusting for age, sex, sociodemographic factors and CD4 count, liver fibrosis/cirrhosis was strongly associated with HBV (aOR 8.80, 95% CI [2.46–31.45]; p < 0.001) and diabetes/prediabetes (aOR 9.89, 95% CI [1.14–85.67]; p < 0.037)." (PMID 35743539, 2022). "Pancreatic islet–derived CD4 TCRs responding to insulin are more frequent in those who develop diabetes." (PMID 35998036, 2022). "CRAMP deficiency further aggravated increases in the frequencies of pancreatic α4β7+CD8+ and α4β7+CD4+ cells in C. rodentium-accelerated diabetes, which were significantly inhibited by exogenous CRAMP treatment." (PMID 35547774, 2022). "The leading PAFs for ARD in PLWHs were declined eGFR (39.68%, 95% CI 17.41–55.83%) and CD4 count<200 cells/μL (39.61%, 95% CI 26.59–50.43%), which were higher than that of diabetes (10.19%, 95% CI 5.04–15.05%)." (PMID 33620297, 2021). "The predictor variables included demographic and clinical characteristics such as age, gender, body mass index (BMI), viral load, CD4 cell count and a history of hypertension, diabetes mellitus or dyslipidaemia." (PMID 34230861, 2021). "c-Maf SUMOylation in CD4+ T cells has been shown to regulate IL-21-mediated diabetes in NOD mice in an inverse manner." (PMID 34336833, 2021). "In our early studies on the role of CD4 T cells in the NOD mouse, we isolated and characterized a panel of islet-reactive, diabetes-inducing CD4+ T cell clones, the BDC (Barbara Davis Center) panel." (PMID 33673706, 2021).
diabetes (continued). "Follicular helper T-cells (Tfh) of diabetic patients express elevated levels of C-X-C motif chemokine receptor 5 (CXCR5), and there is a dysregulation of circulating CD4+ CXCR5 + T-cells in diabetes patients." (PMID 34516309, 2021). "Similar to the adoptive transfer with total splenocytes, CD4+ T cells from BDC2.5+Il-10-/- NOD mice induced rapid onset of diabetes compared to their counterparts from BDC2.5+Il-10+/+ NOD mice." (PMID 34394099, 2021). "Clinical variables included age, sex, hypertension, diabetes, tumor grade, Fuhrman grade, histology, surgery, and CD4+ T lymphocyte count." (PMID 34917092, 2021). "Those with elevated CRP (>3 mg/L) were likely to have higher BMI, to have diabetes and to have elevated 10-year predicted CVD risk and to have a lower estimated CD4 T-cell count." (PMID 34117263, 2021). "FABP7 was significantly correlated with “breakdown of CD4+ T-cell peripheral tolerance in type 1 diabetes mellitus”, “immune response_IL-12 signaling pathway”, and “immune response_T-cell co-signaling receptors, schema” in CRC development." (PMID 34680577, 2021). "There was a significantly higher number (p = 0.022) of CD3+ CD4+ T cells in the group of patients with newly diagnosed diabetes (<3 months from diagnosis) than in the control group." (PMID 34830017, 2021). "Along with the development of diabetes and islet infiltration by CD4+ and CD8+ T cells, a dramatic decrease of β-cell mass and a decrease in α-cell mass were observed in diabetic YES-RIP-hB7.1 mice, as previously been reported in NOD mice." (PMID 34721418, 2021). "Most importantly, Il-10 deficiency changed the function of CD4+ T cells as BDC2.5+Il-10-/- CD4+ T cells were more pathogenic and induced rapid diabetes onset in NOD.scid mice compared with those CD4+ T cells from BDC2.5+Il-10+/+ NOD mice." (PMID 34394099, 2021). "It was shown that the percentage (p = 0.018) and the number (p = 0.003) of lymphocytes with the CD4+ TLR2+ phenotype in the peripheral blood of patients with type 1 diabetes mellitus were higher than in the control group." (PMID 34830017, 2021). "Primary CD4 T cell lines reactive to Ins1C:51-61 were able to transfer diabetes in NOD.Rag1−/− recipients." (PMID 33822842, 2021). "The number (p = 0.040) of CD4+ TLR2+ T cells in children with long-term type 1 diabetes mellitus was higher than in the control group." (PMID 34830017, 2021). "After adjusting for history of hypertension and diabetes, shortness of breath (Mode 2), the HR for in-hospital death in the group with lower CD4+T cell level was 13.631 (95%CI: 3.190–58.243, P< 0.001)." (PMID 33435865, 2021). "In people with diabetes, the number of CD4+ T cells and CD20 cells positively correlates with proteinuria." (PMID 34506229, 2021). "It is worth noting here that the suppressor function of CD4+/CD25+ T cells is defective in diabetes." (PMID 34571886, 2021). "FABP9 was significantly correlated with “putative role of Tregs in COPD”, “breakdown of CD4+ T-cell peripheral tolerance in type 1 diabetes mellitus”, and “immune response_IL-16 signaling pathway” in the development of CRC." (PMID 34680577, 2021). "Transfer of CD4+ T cells from these mice or cotransfer repopulated B cells with autoreactive T cells suppressed diabetes development, implying that depletion of B cells generated both B and T cells with regulatory functions." (PMID 34778464, 2021). "Similar to the reports above, comparisons in the present study showed that PJP+ IIM patients had been receiving higher doses of corticosteroids and had a higher prevalence of diabetes, lower albumin level, and low CD4+ T cell counts." (PMID 34481528, 2021). "Several studies in the mice model of streptozotocin-induced diabetes mellitus, and of T2D patients, report an increased CD4+ T cell proliferation but decreased IFN-γ production, exhibiting a dysfunctional phenotype." (PMID 34944407, 2021).